LAG3 (lymphocyte activating 3)
Diseases named in the same sentence as LAG3 in open-access papers (continued):
Sharing a sentence is not in itself a finding about the gene and the disease.
breast cancer (continued). "Therefore, targeting the LAG3‐LGALS3 and TIGIT‐NECTIN2 pairs may be an effective strategy for treating liver and brain metastases of breast cancer." (PMID 36529697, 2023). "In the present study, to better understand the importance of LAG-3 in breast cancer and its interaction and correlation with other immune checkpoints, such as CTLA-4 and PD-1, we evaluated the prognostic significance of LAG-3 by gene-expression analysis in a cohort of 461 breast cancer patients." (PMID 36289918, 2022). "Many emerging immune checkpoints targets, e.g., lymphocyte activation gene-3 (LAG-3), T-cell immunoglobulin and mucin domain-containing protein 3 (TIM-3), T-cell immunoglobulin and ITIM domain (TIGIT) and B7-H3, are either in the clinical trial or under active development in breast cancer." (PMID 34439387, 2021). "LAG3 did not have a significant association with DFS [HR 1.02, 95% confidence interval (CI) 0.77-1.37; P = 0.87], with subgroup analysis showing worse DFS in patients with lymphoma and improved DFS in those with breast cancer." (PMID 31681578, 2019). "However, the role of LAG-3+ lymphocytes in human breast cancer (BC) is still not conclusive." (PMID 36761428, 2023). "By histological type, medullary breast cancers not surprisingly exhibited higher levels of CD8 iTILs and LAG-3 sTILs, whereas lobular carcinomas had lower levels of these immune cells compared to the other subtypes (p-value = 0.03)." (PMID 35954471, 2022). "Considering the lack of knowledge, feline serum VISTA levels from cats with mammary carcinoma were compared with healthy controls, and with serum levels of PD-1/PD-L1, CTLA-4, LAG-3, IL-6, and TNF-α." (PMID 34771722, 2021). "Next, we examined the expression of PD-1, CTLA-4, LAG-3, TIM-3, FoxP3, and Helios in CD4+CD25− T cell subset in the presence or absence of breast cancer cells." (PMID 31614877, 2019). "Breast cancer cells also upregulated the expression of PD-1, TIM-3 and/or LAG-3, but not CTLA-4, in CD4+CD25+ T cells (comprising of activated T cells and Tregs)." (PMID 31614877, 2019). "Collectively, these data show that in breast cancer patients, circulating NKT cell number may not correlate with function and provide a subset of biomarkers TNF-α, LAG3, and LIGHT, which can be used to assess immune function." (PMID 39596374, 2024). "Furthermore, PD-1+ T cells do not co-express LAG-3, TIM-3 or CTLA-4, which may suggest that PD-1+ T cells in breast cancer may not suffer from exhaustion, or at least support the argument that PD-1 expression alone does not indicate T cell exhaustion." (PMID 30728081, 2019). "However, in peripheral blood mononuclear cells of patients with breast cancer, PD-L1 and TIGIT expressions could be regulated by DNA methylation epigenetic machinery; however, no changes in Tim-3, CTLA-4, and LAG-3 expressions were observed compared to those in healthy donors." (PMID 34504800, 2021).
glioma (83 papers, 2017 to 2025). A benign or malignant brain and spinal cord tumor that arises from glial cells (astrocytes, oligodendrocytes, ependymal cells). "Elevated expression of LAG3 was associated with a poor prognosis in kidney clear cell carcinoma (P < 0.0001), lower-grade glioma (P = 0.0302), ocular melanoma (P < 0.0001), and lower-grade glioma and glioblastoma (P < 0.0001)." (PMID 38062416, 2023). "For instance, B7‐H3, TIM3 and LAG3 were more likely to associate with the occurrence of glioma, while B7‐H3, TIM3, BTLA, PD‐1, and PD‐L1 were more likely to associate with the development of glioma via immunosuppression." (PMID 35668574, 2023). "Evidence suggests that in glioma LAG-3 expression is associated with CD3+, CD8+, CD20+ and PD-1+ tumor-infiltrating lymphocytes (TILs) and PD-L1+ tumor cells and hence were more frequently noted in samples with an active inflammatory microenvironment." (PMID 36077354, 2022). "LAG-3 is only rarely expressed on TILs in IDH-wildtype glioma and associated with active inflammatory milieu as defined by higher TIL density." (PMID 33651248, 2021). "Our findings demonstrated that T cells in high-risk glioma shared key features of T cell exhaustion such as the expression of co-inhibitory receptors including PD-1, LAG-3, and TIM-3, as observed in chronic infections." (PMID 33796538, 2021). "Our data therefore underline the heterogenous composition of the glioma inflammatory microenvironment cohort also in terms of LAG-3+ TIL density." (PMID 33651248, 2021). "Another molecule associated to T cell dysfunction, LAG-3, was present on all T cells infiltrating grade II to IV gliomas, although at lower levels than PD-1, and its expression peaked in grade III gliomas." (PMID 30813960, 2019). "Additionally, we observed a correlation between FH expression and higher expression of the immune checkpoint molecules TIM3 and LAG3, shown to render the glioma microenvironment immunosuppressive and associated with worse prognosis for patients with glioma." (PMID 39378431, 2025). "Moreover, the high levels of LAG-3 expression were associated with lower OS and worse outcomes in both low-grade and high-grade gliomas." (PMID 37509517, 2023). "Preclinical studies have shown that dual blockade of LAG3 and PD-1 can significantly suppress glioma progression." (PMID 40661083, 2025). "We also observed positive correlations between the risk score and several immune checkpoint genes, including SIGLEC7, PDCD1, LILRB2, HAVCR2, and LAG3, which have been tied to poor prognosis in glioma." (PMID 41180518, 2025). "A preclinical study in mice showed that blocking LAG-3 alone or in combination with an anti-PD-1 antibody led to a regression of gliomas." (PMID 39531784, 2024). "This expression pattern suggests a nuanced role for LAG-3 in the immune contexture of gliomas, potentially contributing to immune evasion mechanisms employed by tumor cells." (PMID 38342925, 2024). "In glioma, LAG-3 is a potential marker for the mesenchymal molecular subtype, according to the Cancer Genome Atlas transcriptional classification, and warrants further exploration for potential clinical application." (PMID 38342925, 2024). "After that, we found that 6 immune checkpoints (CD274, CTLA4, LAG3, LGALS9, PDCD1, and PDCD1LG2) were significantly upregulated in the high-glioma-risk group, while RDH5, RDH10 and DHRS3 simultaneously have a substantial positive connection with PDCD1LG2." (PMID 39465792, 2024). "The glioma microenvironment is influenced by the interaction of LAG-3 with various cellular components, including Tregs and dendritic cells (DCs)." (PMID 38342925, 2024). "The study also showed that LAG-3 is expressed in human gliomas, which served as the basis for subsequent clinical trials." (PMID 39531784, 2024). "In glioma, LAG-3 is expressed on a subset of TILs, particularly in IDH-wildtype gliomas, and is associated with a more active inflammatory milieu characterized by higher TIL density." (PMID 38342925, 2024).
glioma (continued). "We found that in patients with glioma, B7‐H3, LAG3 and TIM3 were significantly raised, while the expression of PD‐L1, BTLA, TIGIT, PD‐1 and CTLA4 did not seem to be significantly different from those of normal individuals." (PMID 35668574, 2023). "It has been shown that LAG3 is realized to be highly expressed in glioma patients, but the sample size is small and further experimental validation is needed." (PMID 37351101, 2023). "The expression of LAG3 has been detected in 10% of gliomas biopsies in one study and in 66% of samples in other study." (PMID 36186781, 2022). "LAG3 can promote glioma progression by regulating the proliferation, migration, and invasion of glioma cells, and inhibition of LAG3 suppresses the invasion of ovarian cancer." (PMID 36186438, 2022). "Nevertheless, Clinicaltrials.gov portal reports only a few ongoing studies regarding LAG3 inhibitors in renal and esophageal tumors, in glioma, in leukemia, in testis cancer." (PMID 36224560, 2022). "Studies have confirmed that the increased of immune checkpoints such as PD-L1, CTLA-4, TIM-3, and LAG3 in glioma helps tumor immune evasion, leading to T cell dysfunction." (PMID 35309512, 2022). "Overexpression of LAG-3 plays a key role in promoting tumor growth in high-grade gliomas as well as in low-grade gliomas, and its higher level predicts a prognosis of worse overall survival." (PMID 36077354, 2022). "PIMREG correlated with CTLA-4, PDCD1, LAG3 and other immune checkpoints in glioma and correlated with the patient’s response to immunotherapy." (PMID 35928818, 2022). "Still, data on LAG-3 expression in glioma patients is rare and the here presented cohort is among the largest published so far." (PMID 33651248, 2021). "In glioma, a preclinical study using a syngenic mouse model showed that treatment with anti-LAG-3 antibodies either alone or in combination with PD-1 inhibition is effective and results in prolonged survival." (PMID 33651248, 2021). "In line with our results, a transcriptomic study based on The Cancer Genome Atlas (TCGA) data showed that glioblastomas (and even more distinctly low-grade gliomas) were among the tumors with the lowest expression of LAG-3 as compared to other malignancies." (PMID 33651248, 2021). "Studies have confirmed that the increased immune checkpoints such as PD-L1, CTLA-4, TIM-3, and LAG3 in glioma help tumor immune evasion, leading to T-cell dysfunction." (PMID 35211508, 2021). "As only IDH-wt glioblastoma cases had LAG-3+ TILs, survival analysis according to LAG-3 expression was only performed in this subgroup to exclude the prognostic impact of different glioma subgroups." (PMID 33651248, 2021). "We aimed to investigate lymphocyte activation gene 3 (LAG-3), an inhibitory receptor on immune cells and target of second-generation immune checkpoint inhibitors, in glioma." (PMID 33651248, 2021). "Two separate phase I clinical trials in glioma patients are ongoing, where a combination of LAG-3-specific blocking mAbs with PD-1 inhibitors has been used (NCT02658981, NCT03493932)." (PMID 34298735, 2021). "Here, we show that within the glioma TME, treatment with IL-12 leads to a decreased proportion of CAR-T cells expressing high levels of PD1 and LAG3, inhibitory receptors which have been associated with reduced functional properties of CD8+ T cells." (PMID 33469002, 2021). "At the same time, in bladder cancer and glioma, LAG3 demonstrated an adverse protective role." (PMID 39064019, 2024). "These interactions underscore the potential of LAG-3 as a target in glioma immunotherapy." (PMID 38342925, 2024). "Notably, we also found that 6 immune checkpoints were significantly upregulated in the high-glioma-risk group, including CD274, CTLA4, LAG3, LGALS9, PDCD1, and PDCD1LG2." (PMID 39465792, 2024). "LAG-3 expression was also shown to be higher in glioma patients compared to healthy controls." (PMID 37509517, 2023).
glioma (continued). "High LAG-3 expression levels have been associated with poorer prognosis for renal cell carcinoma (RCC), poor overall survival (OS) of patients with either high- or low-grade glioma, and low disease-free survival in patients with pancreatic cancer." (PMID 37670328, 2023). "A study conducted by Maximilian and his group about the LAG-3 expression in human glioma suggested the diversity of immune microenvironment composition of glioma, and the combination of anti-PD-1 with LAG-3 checkpoint inhibitor is more effective at an earlier point." (PMID 37445721, 2023). "Furthermore, we found that 5 immune inhibitors (KDR, TIGIT, VTCN1, LAG3 and ADORA2A) and 2 immune stimulators (ICOS and TNFRSF25) were significantly associated with HIC2 in gliomas." (PMID 36650953, 2023). "Similarly, α-OX40 is reported to reverse intracranial T cell exhaustion, evidenced by PD-1, TIM-3, or LAG-3 expression in GL261 glioma cells." (PMID 35681672, 2022). "The corresponding value of PDCD1 and LAG3 has also been demonstrated in successive glioma studies." (PMID 35896732, 2022). "Although the expression of LAG3 is controversial in gliomas, it is possible that the expression of this immunological checkpoint could raise in response to the inflammatory infiltration induced by immunotherapeutic strategies, such as anti-mIDH vaccines." (PMID 36186781, 2022). "Indeed, high glioma grades showed significantly higher PD-1, Tim-3 and LAG-3 expressions compared to low grades, exhibiting a similar expression profile to VISTA (p < 0.0001)." (PMID 34728682, 2021). "Here, we investigated LAG-3 expression in the inflammatory microenvironment of glioma." (PMID 33651248, 2021). "LAG-3 is expressed in gliomas with a particularly active immune microenvironment." (PMID 34298735, 2021). "In the present work, most of these exhaustion markers [TIGIT, CEACAM1, CTLA4, LAG3, PD-1, PD-L1, and TIM3] were highly expressed in the high-risk subtype, indicating an elevated level of immune exhaustion in the tumors of high-risk glioma patients." (PMID 34778248, 2021). "In conclusion, LAG-3 is only expressed in a small number of human glioma samples." (PMID 33651248, 2021). "Interestingly, in patients with glioblastoma multiforme, CD8A expression was associated with LAG-3 expression and not with PD-L1 expression in contrast with low-grade glioma." (PMID 37509517, 2023). "Thus, it can be inferred that the combination of NR2F6 blockade with other ICIs, such as PD-1, LAG-3, and B7-H3, may be an alternative treatment method for glioma patients." (PMID 37575237, 2023). "Studies have shown that the upregulation of immune checkpoints such as PD-L1, CTLA-4, TIM-3, and LAG3 in glioma helps tumor immune evasion, leading to T cell dysfunction, suggesting that METTL7B may promote tumor immune evasion by upregulating the expression of immune checkpoints." (PMID 33996568, 2021). "However, systematic data on LAG-3 expression in human glioma tissue are missing so far." (PMID 33651248, 2021). "LAG3 and HAVCR2 (TIM-3) have emerged as important targets in the context of immunotherapy resistance in glioma." (PMID 40661083, 2025). "LAG-3 expression is correlated with poor prognosis in renal clear cell carcinoma (RCC), low-grade glioma, uveal melanoma, hepatocellular carcinoma (HCC), head and neck squamous cell carcinoma, and non-small cell lung cancer." (PMID 39751894, 2025). "The expression of the more well-known immune-related targets in glioma, such as CTLA4, PDCD1 (PD-1), CD274 (PD-L1), LAG-3, and CD47, was then examined." (PMID 38396140, 2024). "Our data revealed a significant correlation between the expression levels of immune checkpoint molecules (CD274, CTLA4, HAVCR2, LAG3, PDCD1, PDCD1LG2, TIGIT, and SIGLEC15) and RAB32 in high-grade gliomas (HGG)." (PMID 39668831, 2024).
glioma (continued). "Signature scores of immune checkpoints, including CTLA4, LAG3, PDCD1, PD-L1, PD-L2 and TIGIT as well as the top five marker genes within each TAM subset were calculated using RNA-seq data from TCGA low grade glioma patients." (PMID 38515213, 2024). "The major mechanism that impacts T cells’ function in glioma is exhaustion which includes an increase in the expression of inhibitory receptors like PD-1, TIM-3, and Lag-3." (PMID 39452154, 2024). "Immune checkpoint genes such as PD-L1, PD-1, CTLA4, LAG3, HAVCR2, PDCD1LG2 were positively correlated with IGFBP5 in glioma." (PMID 38164271, 2024). "In glioma, TILs were severely hypofunctional due to the co-expression of PD-1, TIM-3, and LAG-3 which will prevent from lysing tumor cells through cellular programming." (PMID 39452154, 2024). "In our study, Siglec15 was broadly and positively correlated with immune checkpoints that have been reported as potential biomarkers of glioma, such as PD1, PDL1, PDL2, Lag3, CTLA4, TIGIT, CD276 (B7-H3), IDO1 and CD47." (PMID 37325664, 2023). "Gliomas of CDNP-R848 treated mice depicted an altered T cell composition with increased CD4+ T cell proliferation and decreased Lag3-mediated T cell exhaustion, likely driven by IL-12 upregulation." (PMID 36774352, 2023). "We observed that PTPN18 expression was positively correlated with six immunosuppressive genes (PD-L1, PD-1, CTLA4, LAG3, HAVCR2, and CD244) in most cancers, including glioma." (PMID 36846716, 2023). "We further analyzed the expression distribution of immune checkpoints gene (including CD274, CTLA4, HAVCR2, LAG3, PDCD1, PDCD1LG2, TIGIT, and SIGLEC15) in glioma tissues and normal brain tissues using the TCGA database." (PMID 36915038, 2023). "PIMREG expression in glioma was positively correlated with HAVCR2 (P = 2e-10, Cor = 0.24), LAG3 (P = 1.5e-15." (PMID 35928818, 2022). "We investigated the immune checkpoint expression in glioma specimens and uncovered that CD274 (PD-L1), PDCD1, PDCD1LG2, CTLA4, CD276, HAVCR2, and LAG3 were significantly overexpressed in the high DDR score subtype." (PMID 35720326, 2022). "Previous studies have identified different immune checkpoint molecules in gliomas, such as CTLA-4, TIM-3, PD-1, CD48, and LAG3." (PMID 35832194, 2022). "The results showed that significant positive correlations existed between MELK expression and B7-H3, CTLA4, LAG3, PD-1, PD-L1, and TIM3 expression in glioma." (PMID 36353126, 2022). "The highest expression was detected in the WHO glioma grade IV tumors (CD274 p = 2.0e − 08, HAVCR2 p = 1.5e − 09, LAG3 p = 9.7e − 05, PDCD1 p = 5.6e − 05, PDCD1LG2 p = 2.2e − 18, and SIGLEC15 p = 4.3e − 05)." (PMID 35198632, 2022). "In fact, in glioma case different immune checkpoint molecules have been described such as CTLA-4, PD-1, TIM-3, and LAG-3; each of these receptors has corresponding ligands." (PMID 34305910, 2021). "TIME cluster A exhibited the high expression profiles of ZEB1, TNF, and LAG3; while GZMA, CXCL9, CXCL10, and CD8A were relatively overexpressed in TIME cluster C. EMT is a common process of paramount importance in glioma occurrence and invasion." (PMID 34650972, 2021). "The GASC score was positively correlated with PD-1, PD-L1, PD-L2, TL1A, TIM3, Galactin-9, CTLA-4, CD80, CD86, CD155, LAG3, and CIITA in all glioma population and the HGG population." (PMID 33996602, 2021). "At last, VISTA mRNA expression levels appeared to be the highest in all glioma cases (low and high grade) when compared to those of other critical immune checkpoints, Tim-3, PD-1, CTLA-4, LAG-3 and TIGIT (p < 0.0001)." (PMID 34728682, 2021). "In newly diagnosed grade 3 gliomas, the descending frequency of expression was A2aR > PD-1 > CD39 > CD73 > TIGIT > LAG-3 > BLTA > CD160 > CTLA-4 > KIR > TIM3 on CD8+ T cells." (PMID 32721947, 2020).